IFIT1B (interferon induced protein with tetratricopeptide repeats 1B)
Description:
IFIT1B is likely non-functional, lacking the critical antiviral role of IFIT1. Unlike IFIT1, which is essential in the innate immune response as part of an interferon-dependent multiprotein complex, IFIT1B does not prevent the translation of viral RNAs that lack host-specific 2'-O-methylation at their 5' cap. Consequently, it probably cannot inhibit their translation by competing with the host translation machinery.
Synonyms: IFIT1L; bA149I23.6
Tractability: PROTAC: ubiquitination databases record sites on it.
Gene: Protein-coding gene on chromosome 10 (89,378,056 to 89,385,205, forward strand). Ensembl gene ENSG00000204010.
Gene Ontology:
Molecular function: protein binding; RNA sequestering activity; RNA binding
Biological process: negative regulation of viral translation; antiviral innate immune response; cellular response to cytokine stimulus; response to other organism
Cellular component: cytosol
Genetic constraint (gnomAD): Loss-of-function variants: 3 observed, 2.64 expected, observed/expected ratio (o/e) 1.14, 90% interval 0.47 to 1.89. That is too few expected variants to judge how well the gene tolerates losing a copy. Missense variants: 545 observed, 586.48 expected, observed/expected ratio (o/e) 0.93, 90% interval 0.87 to 1. Synonymous variants: 196 observed, 215.24 expected, observed/expected ratio (o/e) 0.91, 90% interval 0.81 to 1.02.
Homologues: Orthologues: guinea pig IFIT1B (64% identical), chimpanzee IFIT1B (60% identical), rat Ifit1bl (59% identical), rat Ifit1 (57% identical), mouse Ifit1bl1 (57% identical), mouse Ifit1 (57% identical), mouse Ifit1bl2 (54% identical), tropical clawed frog ifit5l (38% identical), tropical clawed frog ifit5 (37% identical), tropical clawed frog ifit1b (36% identical), zebrafish ifit10 (33% identical), zebrafish ifit11 (32% identical), and 5 more. Paralogues in human: IFIT1 (67% identical), IFIT5 (55% identical), IFIT3 (44% identical), IFIT2 (43% identical).
Diseases named in the same sentence as IFIT1B in open-access papers:
IFIT1B is named in the same sentence as 7 diseases in open-access papers, as found by Europe PMC text mining. Sharing a sentence is not in itself a finding about the gene and the disease. The quoted sentences say what the papers report.
viral infections (2 papers, 2016 to 2020). "IFIT1B expression can be stimulated by interferons during viral infections." (PMID 32640699, 2020). "However, most previous studies investigating mRNA cap requirements for IFIT1B-mediated growth inhibition have been carried out in the context of a virus infection under interferon-induced conditions." (PMID 27240734, 2016).
infection (3 papers, 2019 to 2022). The state of being infected such as from the introduction of a foreign agent such as serum, vaccine, antigenic substance or organism. "Before infection, the cis-element was linked to IFIT1B and IFIT5, which were dynamically reshuffled to link with IFIT1, IFIT2, and IFIT3 after infection." (PMID 36195603, 2022).
tumor (2 papers, 2020). "Besides, the protein expression of IFIT1B was not significantly different between tumor and normal lung tissue." (PMID 32087603, 2020).
IFIT1B also shares sentences with these, for which no sentence is quoted: Alzheimer disease (1 paper); cardiomyopathies (1); cardiovascular diseases (1); hepatitis C (1).